LINC01936 (long independently transcribed non-coding RNA 1936)
Gene: Long non-coding RNA gene on chromosome 2 (30,346,623 to 30,361,014, forward strand). Ensembl gene ENSG00000235997.
Diseases named in the same sentence as LINC01936 in open-access papers:
LINC01936 is named in the same sentence as 2 diseases in open-access papers, as found by Europe PMC text mining. Sharing a sentence is not in itself a finding about the gene and the disease. The quoted sentences say what the papers report.
tumor (3 papers, 2021 to 2023). "In present study, we found that LINC01936 could inhibit the proliferation, migration and invasion of LUSC cells and promote cell apoptosis; which indicated that LINC01936 might serve as a tumor suppressor gene to affect LUSC development." (PMID 38084139, 2023).
LINC01936 also shares sentences with these, for which no sentence is quoted: lung squamous cell carcinoma (1 paper).